RSAD1 (radical S-adenosyl methionine domain containing 1)
Description:
May be a heme chaperone, appears to bind heme. Homologous bacterial proteins do not have oxygen-independent coproporphyrinogen-III oxidase activity (Probable). Binds 1 [4Fe-4S] cluster. The cluster is coordinated with 3 cysteines and an exchangeable S-adenosyl-L-methionine (By similarity).
Synonyms: FLJ11164; HemW
Tractability: PROTAC: ubiquitination databases record sites on it.
Gene: Protein-coding gene on chromosome 17 (50,478,820 to 50,485,984, forward strand). Ensembl gene ENSG00000136444.
Subcellular location: Mitochondrion
Subcellular location (Human Protein Atlas): Mitochondria
Gene Ontology:
Molecular function: heme binding; 4 iron, 4 sulfur cluster binding; catalytic activity; coproporphyrinogen oxidase activity; iron-sulfur cluster binding
Biological process: porphyrin-containing compound biosynthetic process
Cellular component: mitochondrion; cytoplasm
Genetic constraint (gnomAD): Loss-of-function variants: 38 observed, 47.46 expected, observed/expected ratio (o/e) 0.8, 90% interval 0.62 to 1.05. The upper end of that interval is the gene's LOEUF score, 1.05, which puts it in group 4 of 6, group 1 being the genes least tolerant of losing a copy. Missense variants: 635 observed, 563.02 expected, observed/expected ratio (o/e) 1.13, 90% interval 1.06 to 1.2. Synonymous variants: 260 observed, 240.03 expected, observed/expected ratio (o/e) 1.08, 90% interval 0.98 to 1.2.
Homologues: Orthologues: chimpanzee RSAD1 (99% identical), macaque RSAD1 (89% identical), pig RSAD1 (87% identical), rabbit RSAD1 (87% identical), dog RSAD1 (86% identical), guinea pig RSAD1 (85% identical), mouse Rsad1 (85% identical), rat Rsad1 (78% identical), tropical clawed frog rsad1 (61% identical), zebrafish rsad1 (55% identical).
Diseases named in the same sentence as RSAD1 in open-access papers:
RSAD1 is named in the same sentence as 2 diseases in open-access papers, as found by Europe PMC text mining. Sharing a sentence is not in itself a finding about the gene and the disease. The quoted sentences say what the papers report.
virus infection (1 paper, 2022). "RSAD1 can widely activate E3 ligase and increase proteasome-mediated protein degradation upon virus infection." (PMID 36071497, 2022).
RSAD1 also shares sentences with these, for which no sentence is quoted: colorectal cancer (1 paper).